CKS2 (CDC28 protein kinase regulatory subunit 2)
Diseases named in the same sentence as CKS2 in open-access papers (continued):
Sharing a sentence is not in itself a finding about the gene and the disease.
liver cancer (4 papers, 2020 to 2025). An epithelial or non-epithelial malignant neoplasm that arises from the liver. "Recent studies have shown that CKS2 is associated with the occurrence and progression of liver cancer." (PMID 39188686, 2024). "In addition, studies have also shown that CKS2 levels are significantly elevated in HCC tissues, and high expression of CKS2 may be significantly associated with the malignant phenotype of cancer cells and poor prognosis in patients with liver cancer." (PMID 39188686, 2024). "Meanwhile, multivariate regression analysis showed that the overall survival rate of liver cancer patients with high CKS2 expression was significantly lower than that of patients with low CKS2 expression." (PMID 39188686, 2024).
colon carcinoma (3 papers, 2006 to 2024). "CKS2 is involved in cell cycle control, and its activation has been associated with high proliferation of lymphoma cells and incidence of metastasis in colon carcinomas." (PMID 17054779, 2006). "However, the potential interplay between CKS2 and ferroptosis in colon cancer (CC) remains unclear." (PMID 39548421, 2024).
lung carcinoma (3 papers, 2015 to 2024). "The relationship between CKS2 and RMI2 and lung cancer has not yet been reported." (PMID 33083148, 2020).
lymph node metastasis (3 papers, 2022 to 2024). "Furthermore, we found that CKS2 was associated with pathological tumor stage, lymph node metastasis, and the occurrence of STAS in patients." (PMID 36010686, 2022). "The upregulated CKS2 was significantly related to the lymph node metastasis and advanced clinical grade of endometrial carcinoma patients (p < 0.001)." (PMID 35693634, 2022). "Moreover, endometrial carcinoma patients with lymph node metastasis presented notably higher CKS2 expression than endometrial carcinoma patients without lymph node metastasis (p < 0.001)." (PMID 35693634, 2022).
meningioma (3 papers, 2007 to 2019). A generally slow growing tumor attached to the dura mater. "In a microarray study of 23 meningiomas (10 WHO°I, 10 WHO°II, 3 WHO°III) and a validation set of 65 meningiomas (41 WHO°I, 24 WHO° II or III) the prognostic value of a CKS2/LEPR index in meningiomas was assumed." (PMID 26894859, 2016). "In addition, we found induction of IGFBP3, CENPF, CKS2 and reduction of LTBP2, PTPRF in high-grade meningiomas as previously reported." (PMID 17937814, 2007). "The positive correlation of PRKACA with NF2 gene expression, which is downregulated in meningioma, may support this view, as well as the negative correlation of PRKACA expression with the four upregulated genes typically found in recurrent meningiomas (CDC2, MLF1IP, CKS2, and PRC1)." (PMID 31671850, 2019).
pancreatic cancer (3 papers, 2018 to 2023). "CKS2 overexpression may be associated with shorter survival of patients with PDAC, probably due to CKS2 function in promoting proliferation of pancreatic cancer cells." (PMID 29764514, 2018).
papillary thyroid carcinoma (3 papers, 2018 to 2025). "Moreover, the association between miR-7-5p and the CKS2 gene has been demonstrated only in a study conducted on papillary thyroid carcinoma tissues and cell lines." (PMID 41010991, 2025). "In a papillary thyroid carcinoma, miR-26a and miR-7 modulates tumor growth and tumorigenesis by targeting CKS2." (PMID 29760609, 2018). "In that study, it was reported that the upregulation of miR-7-5p inhibited cell proliferation, invasion, and migration by targeting CKS2, suggesting that the miR-7-5p/CKS2 axis could serve as a foundation for developing miRNA-targeted therapies in papillary thyroid carcinoma." (PMID 41010991, 2025).
retinoblastoma (3 papers, 2022 to 2025). A malignant tumor that originates in the nuclear layer of the retina. "In the Y79 retinoblastoma cell line, the deletion of CKS2 resulted in reduced cell proliferation, delayed DNA replication, and reduced clone growth." (PMID 38920989, 2024). "Depletion of CKS2 in Y79 retinoblastoma cell line led to reduced cell proliferation, delayed DNA replication and decreased clonogenic growth." (PMID 36096885, 2022). "We also knocked down CKS2 with two shRNAs in human retinoblastoma WERI-Rb-1 cells and found that downregulation of CKS2 in this cell type led to similar phenotypes as well including cell proliferation, colony formation and EdU staining." (PMID 36096885, 2022). "This study discovered E2F1/CKS2/PTEN signaling axis regulates malignant phenotypes in pediatric retinoblastoma, and CKS2 may serve as a potential therapeutic target for this disease." (PMID 36096885, 2022). "By screening a set of cancer-related genes directly regulated by transcription factor E2F1 and a series of experimental validations, we demonstrated that E2F1/CKS2/PTEN signaling axis regulates malignant phenotypes in RB and CKS2 may serve as a potential therapeutic target for retinoblastoma." (PMID 36096885, 2022). "In pediatric retinoblastoma, E2F1 could increase the expression of CKS2 via binding to its promotor, thereby promoting the promotes cell proliferation and tumor formation." (PMID 40070576, 2025). "To confirm that E2F1 did play a causal role in promoting transcription of CKS2, we knocked down E2F1 with two short hairpin RNAs (shRNAs) in human retinoblastoma cells (Y79 and WERI-Rb-1) and found that expression of CKS2 was significantly decreased in both RNA and protein levels." (PMID 36096885, 2022).
thyroid cancer (3 papers, 2019 to 2024). "Bioinformatics analysis found that CKS2 is related to invasion and metastasis, and the overexpression of CKS2 contributes to the migration and invasion of thyroid cancer." (PMID 39188686, 2024). "Overexpression of CKS2 contributed to the tumor proliferation, migration, and invasion in thyroid cancer." (PMID 31781310, 2019).
breast tumors (2 papers, 2007 to 2017). "To this end, we first found significant association of the expression profiles of four genes, CDC2, CKS2, DNA2L, and CDC6, with ERβ transcript levels in the breast tumors, consistent with the inverse correlation (high ERβ; low cell cycle/DNA replication genes) observed in the cell line model." (PMID 17428314, 2007). "In order to test the central hypothesis of the study in a more clinically relevant model, the therapeutic response of breast tumors expressing low versus high levels of Cks2 to combination treatment with methotrexate and gemcitabine was analyzed in an orthotopic mouse model." (PMID 29383129, 2017).
cholangiocarcinoma (2 papers, 2022). A carcinoma that arises from the intrahepatic biliary tree (intrahepatic cholangiocarcinoma) or from the junction, or adjacent to the junction, of the right and left hepatic ducts (hilar cholangiocarcinoma). "CKS2 was reported to be overexpressed in cholangiocarcinoma and stimulate the aggressiveness of cholangiocarcinoma by modulating cell cycle progression and mitochondrial caspase-dependent apoptosis." (PMID 35693634, 2022).
leukaemia (2 papers, 2018 to 2024). "Altogether, these analyses revealed a dysregulation of CKS expression in MLLr leukaemia, but also in BCR-ABL positive CML, consistent with putative roles for CKS1B and CKS2 in leukaemogenesis." (PMID 28939057, 2018).
mucinous lung adenocarcinoma (2 papers, 2022 to 2024). "Moreover, CKS2 has a good ability in distinguish stages I–III invasive non-mucinous lung adenocarcinoma patients from healthy samples, indicating that CKS2 has the potential to be used as a diagnostic biomarker for stages I–III invasive non-mucinous lung adenocarcinoma." (PMID 36010686, 2022). "The association of CKS2 expression level with both histological subtype and STAS suggested that CKS2 was connected with the growth pattern of invasive non-mucinous lung adenocarcinoma." (PMID 36010686, 2022).
Multiple Myeloma (2 papers, 2023 to 2025). "Conversely, CKS2 overexpression enhanced malignant proliferation while suppressing apoptotic processes, establishing its functional role in myeloma pathogenesis." (PMID 40092696, 2025). "Transcriptomic profiling via RNA sequencing revealed significant upregulation of cyclin-dependent kinase regulatory subunit 2 (CKS2) in multiple myeloma." (PMID 40092696, 2025). "Based on these findings, we conclude that CKS2 modulates biological functions in multiple myeloma (MM) cells." (PMID 40092696, 2025). "Our mechanistic studies demonstrate that CKS2 knockdown in multiple myeloma (MM) cells induces PTEN upregulation with concomitant suppression of AKT/mTOR phosphorylation." (PMID 40092696, 2025). "We made use of the Tumor Immune Single-cell Hub (TISCH) database and employed Uniform Manifold Approximation and Projection (UMAP) to examine the expression levels of CKS2 and LYZ in single cells obtained from myeloma tissues." (PMID 37580667, 2023).
Alzheimer disease (1 paper, 2024). A progressive, neurodegenerative disease characterized by loss of function and death of nerve cells in several areas of the brain leading to loss of cognitive function such as memory and language. "Conversely, for hub genes identified from upregulated DEGs, Alzheimer’s disease has been linked to CD2, CDC25A, CKS2, LCK, PRKACG, and S100A7." (PMID 39766348, 2024).
bladder tumors (1 paper, 2010). "In the attempt to evaluate a possible role of the studied genes in the development and progression of bladder tumors, we compared the transcript levels of hTR, hTERT and CKS2 in exfoliated cells from superficial low grade (pTa, pT1) or muscle invasive high grade (pT2-4) BC and controls." (PMID 20920335, 2010).
bone marrow disorder (1 paper, 2023). Any disease of the bone marrow. "These phenotypes point to CKS1 and CKS2 as actionable targets in bone marrow disorders where protein quality control and intracellular signaling declines or is hijacked by neoplastic mutations, and indeed we have already demonstrated that inhibition of CKS1 can be “chemoprotective” for healthy HSCs." (PMID 36874381, 2023).
B‐cell lymphomas (1 paper, 2024). "Through an analysis of the CCLE database, we discovered high expression levels of CKS2 in B‐cell lymphomas, with the BL cell line ranking first and the DLBCL cell line ranking second." (PMID 39560180, 2024). "However, there has been limited documentation regarding the expression of the CKS2 gene in B‐cell lymphomas." (PMID 39560180, 2024).
Cirrhosis (1 paper, 2019). A chronic disorder of the liver in which liver tissue becomes scarred and is partially replaced by regenerative nodules and fibrotic tissue resulting in loss of liver function. "Interestingly, CKS2 also gradually increased in the order from normal, inflammation, cirrhosis, dysplasia, and early stage HCC to advanced stage, suggesting that CKS2 might contribute to the progression of HCC." (PMID 31781310, 2019).
colorectal tumors (1 paper, 2006). "Moreover, CKS2 is expressed at significantly higher levels in colorectal tumors with liver metastasis." (PMID 16919171, 2006).
endometrial carcinoma (1 paper, 2022). A malignant tumor arising from the epithelium that lines the cavity of the uterine body. "In the present work, we investigated the molecular mechanisms of CKS2 in endometrial carcinoma via diverse methods of genetic mutation profile analysis, upstream transcriptional analysis, immune correlation analysis, and co-expression analysis." (PMID 35693634, 2022). "In vitro and in vivo experiments should be carried out in future work to validate the functional roles of CKS2 in the development of endometrial carcinoma and the genetic interaction of CKS2 with co-expressed genes." (PMID 35693634, 2022). "CKS2 displayed obvious higher expression in endometrial carcinoma and a favorable distinguishing ability for endometrial carcinoma in the majority of datasets." (PMID 35693634, 2022). "First of all, an incorporated expression matrix from public RNA-seq and microarrays as well as data from in-house tissue microarray uniformly supported the overexpression of CKS2 in endometrial carcinoma." (PMID 35693634, 2022). "Mutation types such as amplification and mRNA occurred with high frequency in the CKS2 gene in endometrial carcinoma patients." (PMID 35693634, 2022). "With regard to the correlation between CKS2 expression and the infiltration level of immune cells in endometrial carcinoma, significant bonds were observed between CKS2 expression and the immune infiltration of B cells, CD4+ T cells, or neutrophils." (PMID 35693634, 2022). "In conclusion, we identified the upregulation of CKS2 in endometrial carcinoma with tissue microarrays, RNA-seq, and other public microarrays." (PMID 35693634, 2022). "The relationship between CKS2 expression and the clinicopathological features of endometrial carcinoma patients from in-house tissue microarray." (PMID 35693634, 2022). "Lastly, we identified the CKS2-correlated genes in endometrial carcinoma via rigorous calculation of DEGs and correlation expression analysis." (PMID 35693634, 2022). "The upregulated CKS2 was significantly related to the clinical progression of endometrial carcinoma patients." (PMID 35693634, 2022). "The relationship between CKS2 expression and the clinicopathological features of endometrial carcinoma patients from the RNA-seq dataset in the TCGA database." (PMID 35693634, 2022). "So far, there has been no research on the overall assessment of the clinicopathological significance of CKS2 in endometrial carcinoma and the molecular basis of CKS2 in the oncogenesis of endometrial carcinoma." (PMID 35693634, 2022). "Pearson correlation analysis results revealed that CKS2 expression was negatively linked with the infiltration level of B cell and CD4+ T cell in endometrial carcinoma (r = −0.125, p = 0.034; r = −0.173, p = 0.003)." (PMID 35693634, 2022). "Herein, we planned to systematically appraise the clinicopathological significance and explore the molecular bases of CKS2 in endometrial carcinoma using multiple detection technologies, including microarrays, RNA-seq, and in-house tissue microarrays." (PMID 35693634, 2022). "Of 455 identified upregulated DEGs and 428 identified downregulated DEGs in endometrial carcinoma, 153 genes positively co-expressed with CKS2 and 101 genes negatively co-expressed with CKS2 were screened out." (PMID 35693634, 2022). "The oncogenic effect of CKS2 in endometrial carcinoma might be driven by the abnormal miRNA/TF mediated upstream transcriptional regulation and activities of co-expressed genes in certain molecular functions or pathways." (PMID 35693634, 2022). "SMD forest plot and SROC curves generated from all included datasets confirmed the overexpression of CKS2 in endometrial carcinoma and the capacity of upregulated CKS2 in discerning endometrial carcinoma from non-cancer endometrium tissues (SMD = 2.10, 95% CI = 0.72–3.48; AUC = 0.96)." (PMID 35693634, 2022).
endometrial carcinoma (continued). "Significant links were found between CKS2 expression and the infiltration level of B cells, CD4+ T cells, and neutrophils in endometrial carcinoma." (PMID 35693634, 2022). "The differentially expressed CKS2 also showed good performance in discriminating endometrial carcinoma from non-cancer endometrium tissues (AUC = 0.944)." (PMID 35693634, 2022). "Kaplan-Meier survival analysis for 535 endometrial carcinoma patients without adjuvant treatment in RNA-seq dataset of TCGA database indicated no significant impact of CKS2 expression on the survival time of endometrial carcinoma patients (hazard ratio (HR) = 0.832, p = 0.536)." (PMID 35693634, 2022). "As shown by the IHC staining results for 301 endometrial carcinoma and 38 non-cancer endometrium tissues, CKS2 expression was remarkably higher in the glandular epithelial cells of endometrial carcinoma tissues than in non-caner endometrium tissue (9.071 ± 1.122; 5.789 ± 1.788, p < 0.001)." (PMID 35693634, 2022). "We assumed that upregulated CKS2 might reshape the tumor microenvironment of endometrial carcinoma by means of inhibiting the population of B cells and CD4+ T cells or increasing the population of neutrophils to contribute to the initiation and progression of endometrial carcinoma." (PMID 35693634, 2022).
esophageal squamous cell carcinoma (1 paper, 2022). Esophageal squamous cell carcinoma (ESCC) is a type of esophageal carcinoma (EC) that can affect any part of the esophagus, but is usually located in the upper or middle third. "In esophageal squamous cell carcinoma, CKS2 expression was significantly higher in cancer tissues, and suppression of CKS2 attenuated the growth of esophageal squamous cell carcinoma." (PMID 35693634, 2022).
Iron deficiency anemia (1 paper, 2025). "To validate these findings, we performed RT-qPCR on bone marrow aspirates from 44 newly diagnosed MM patients and 16 iron-deficiency anemia controls, confirming elevated CKS2 transcript levels in MM samples." (PMID 40092696, 2025).
liver cirrhosis (1 paper, 2019). "Immunohistochemical assays found that high CKS2 expression was closely associated with liver cirrhosis (P = 0.019), poor differentiation (P = 0.02), portal vein invasion (P < 0.001), TNM stage (P = 0.019), tumor metastasis (P = 0.008), and recurrence (P = 0.003)." (PMID 31781310, 2019). "Moreover, elevated CKS2 levels were significantly associated with various clinicopathological features, including liver cirrhosis, differentiation, portal vein invasion, TNM stage, and metastasis." (PMID 31781310, 2019).
Obesity (1 paper, 2022). Accumulation of substantial excess body fat. "Cyclin-dependent kinases (CKs) (i.e., CKS1B, CKS2) are also involved with cell cycle regulation, and inhibitors of CKs have drawn attention to their use in controlling diet-induced obesity." (PMID 36291149, 2022).
osteoarthritis (1 paper, 2025). A noninflammatory degenerative joint disease occurring chiefly in older persons, characterized by degeneration of the articular cartilage, hypertrophy of bone at the margins and changes in the synovial membrane. "This led to the identification of 411 differentially expressed genes (DEGs) related to osteoarthritis, 2485 DEGs among subgroups, as well as 238 intersecting genes and 5 hub genes (MMP13, FAM26F, CHI3L1, TAC1, and CKS2)." (PMID 40216809, 2025).
osteosarcoma (1 paper, 2022). A usually aggressive malignant bone-forming mesenchymal neoplasm, predominantly affecting adolescents and young adults. "Although Kaplan–Meier curves showed no remarkable difference of overall survival rate between OS patients with high and low-CKS2, CKS2 was found up-regulated in proliferating osteosarcoma cells." (PMID 35410253, 2022). "Cyclin-dependent kinase subunit 2 (CKS2) is a member of cyclin dependent kinase subfamily and the relationship between CKS2 and osteosarcoma (OS) remains to be further analyzed." (PMID 35410253, 2022).
rectum adenocarcinoma (1 paper, 2022). An adenocarcinoma arising from the rectum. "Except for explicit renal cell carcinoma, CKS2 methylation levels were lower in all tumor tissues in TCGA compared with normal tissues, including BLCA, HNSC, PAAD, rectum adenocarcinoma (READ), and UCEC." (PMID 35663965, 2022).
vitiligo (1 paper, 2022). Generalized well circumscribed patches of leukoderma that are generally distributed over symmetric body locations and is due to autoimmune destruction of melanocytes. "Further immune infiltration analysis showed that M2 macrophages were involved in the pathogenesis of vitiligo, whereas CKS2 and RRM2 were both related to M2 macrophages." (PMID 36401415, 2022). "This study shows that CKS2 and RRM2 have potential as biomarkers of vitiligo and provides a theoretical basis for a better understanding of the pathogenesis of vitiligo." (PMID 36401415, 2022). "Therefore, CKS2 and RRM2 could be used as potential markers for vitiligo." (PMID 36401415, 2022).